DDX3X (DEAD-box helicase 3 X-linked)
Diseases named in the same sentence as DDX3X in open-access papers (continued):
Sharing a sentence is not in itself a finding about the gene and the disease.
infection (continued). "Mice lacking DDX3X in the hematopoietic system show alterations in the bone marrow and splenic cell populations and are highly susceptible to infection by pathogenic bacteria." (PMID 35874614, 2022). "Therefore, DDX3X is often targeted and hijacked by viruses during infection to evade immune response and promote replication." (PMID 35897696, 2022). "Ddx3xfl/flLysMCre BMDMs showed a significant reduction in secretion of IFN-β and delayed activation of STAT1 (P-STAT1 levels) compared with Ddx3xfl/fl BMDMs upon IAV and IAV–ΔNS1 infection, further establishing a role for DDX3X in IAV-induced type I IFN responses." (PMID 33766561, 2021). "A variety of viruses hijack or target DDX3X to promote infection." (PMID 32033386, 2020). "Notably, the nuclear export of DDX3X via exportin-1 is critical for maximal gene induction, and thereby presumably results in a more effective innate and adaptive immune response to infection, and as demonstrated in our hPIV-3 infectious model." (PMID 31575075, 2019). "This provides an explanation for its strong impact on infection-induced genes and poses the question whether other pathways conveying immunity are influenced by DDX3X as well." (PMID 30475900, 2018). "DDX3X was down-regulated in dengue virus infected cells at later stages of infection." (PMID 29387631, 2017). "However, DDX3X deficiency did not restore NLRP3 activation after IAV–ΔNS1 infection, and we instead observed that CASP1 cleavage was reduced in Ddx3xfl/flLysMCre BMDMs compared with Ddx3xfl/fl BMDMs when infected with IAV." (PMID 33766561, 2021). "The RNA-binding activity of several proteins increased throughout the infection, such as DDX1, DDX3X, DDX5, and HNRNPA1, indicating that SARS-CoV-2 requires these proteins in the replication and transcription processes." (PMID 37314180, 2023). "DDX3X, a member of the highly conserved DEAD-box RNA helicase family, have been demonstrated to be involved in the pathological processes of infection, immunity, and cell survival." (PMID 35178128, 2022). "We indeed observed colocalization of DDX3X and G3BP1 in SGs after IAV–ΔNS1 infection and also after IAV–PR8 infection followed by Ars treatment." (PMID 33766561, 2021). "Transcriptome profiling and ELISA show that exportin-1-dependent export of DDX3X to the cytoplasm strongly impacts IFN-β production and the upregulation of immune genes in response to infection." (PMID 31575075, 2019). "In this context DDX3X was shown to sense viral RNA and to supplement the function of RIG-I and MDA-5 in the early phase of infection." (PMID 30475900, 2018). "DDX3 (DDX3X) can bind poly(I:C) or vesicular stomatitis virus (VSV) RNA and was shown to enhance the IFN-I response to VSV infection by interaction with the RLR-MAVS complex." (PMID 24400006, 2013). "One hundred fifty-seven differentially expressed cellular proteins were identified, including 84 upregulated and 73 downregulated proteins at 48 h post-infection, among which CXCL8, DDX3X, and TRPV2 may play crucial roles in viral propagation." (PMID 39772141, 2024). "Likewise, the 3’ UTRs of Ddx58, Ddx3x, Ddx21, Ifit2 and Ifit3, were significantly shorter in primary BMDMs from Cpsf6+/- mice, and such shortening was more pronounced upon VSV-eGFP infection." (PMID 38416782, 2024). "Although G3bp1−/− iBMDMs formed fewer SGs after IAV–ΔNS1 infection, we still observed SGs containing DDX3X but not G3BP1 in these cells." (PMID 33766561, 2021). "Mice lacking DDX3X during hematopoiesis showed an altered leukocyte composition in bone marrow and spleen and a striking inability to combat infection with Listeria monocytogenes." (PMID 30475900, 2018). "Knock-down of DDX3X did not affect induction of type I interferon response upon infection suggesting that the effect of DDX3X knock-down is independent of the interferon-dependent pathways that DDX3X modulates under normal conditions." (PMID 29387631, 2017).
infection (continued). "In infection models of Snakehead vesiculovirus (SHVV), the viral phosphoprotein (P protein) binds directly to the N-terminal and core domains of host DDX3X, hijacking DDX3X to stabilize P protein by evading autophagic-lysosomal degradation, thereby enhancing viral replication." (PMID 40606174, 2025). "This suggests that both DDX3X and G3BP1 are required for IAV–ΔNS1–induced SGs and led us to hypothesize that disrupting expression of Ddx3x or G3bp1 might restore NLRP3 activation after IAV–ΔNS1 infection." (PMID 33766561, 2021). "Of the 227 BRD4 interactors that were recruited to the BRD4 complex during RSV-infection, we observe that 95 ( 42%) are disrupted to some degree by treatment with ZL0454, including most of the transcription factors described in the earlier section (e.g., c-JUN, CTNNB1, JUP, DDX3X, MTDH)." (PMID 33799525, 2021).
neurodevelopmental disorder (14 papers, 2021 to 2025). A behavioral and cognitive disorder with onset during the developmental period that involves impaired or aberrant development of intellectual, motor, or social functions. "Our study establishes a technical paradigm for a broader investigation of the diverse landscape of DDX3X missense mutations, as well as missense mutations in other genes linked to other neurodevelopmental disorders." (PMID 39836689, 2025). "Research on DDX3X is extensive and spans across diverse disciplines and topics (including fundamental cell biology, oncology, immunology and neurodevelopmental disorders), indicating its broad functions and associations." (PMID 40164730, 2025). "This work establishes a technical and conceptual foundation for future studies, enabling deeper exploration into the diverse landscape of DDX3X mutations and their contribution to neurodevelopmental disorders." (PMID 39836689, 2025). "Remarkably, DDX3X mutations causative of neurodevelopmental disorders also form cytoplasmic hollow condensates, and those composed of an aggressive RNA-binding deficient mutant display low recovery in FRAP." (PMID 39391721, 2024). "In 46,XY males, rare constitutional (germline) mutations in DDX3X cause a neurodevelopmental disorder (‘DDX3X syndrome’)." (PMID 39026797, 2024). "DDX3X variants are increasingly recognised as a common cause of neurodevelopmental disorders in females, with numbers of diagnosed individuals expected to rise as availability of testing increases." (PMID 35536379, 2023). "Loss-of-function of DDX3X is a leading cause of neurodevelopmental disorders (NDD) in females." (PMID 38057330, 2023). "In fact, the combined contribution of the top 26 genes implicated in neurodevelopmental disorders, including CHD8, DYRK1A, and DDX3X, was estimated to be only about 0.04%." (PMID 34099044, 2021). "DHX30, along with other SF2 members such as DDX3X, DDX6, and DDX59, have been strongly implicated in neurodevelopmental disorders." (PMID 34099044, 2021). "Interestingly, stress granule formation has been associated with maintenance of synaptic plasticity through regulation of synaptic activity-dependent local translation and has been linked to genes involved in neurodevelopmental disorders, such as FMR1 and DDX3X." (PMID 34099044, 2021). "This novel or rare clinical feature was not previously reported in the original description of DDX3X neurodevelopmental disorder." (PMID 35392274, 2022). "Yet, the clinical and genetic features of DDX3X neurodevelopmental disorder in the Chinese cohort have not been characterized." (PMID 35392274, 2022). "However, the clinical and genetic features of DDX3X neurodevelopmental disorder in the Chinese cohort have not been described yet." (PMID 35392274, 2022).
hematological malignancies (4 papers, 2017 to 2025). "The identification of these mutated genes helps prioritize targets for functional studies, with DDX3X selected for this study due to its high mutation rate and its known oncogenic role in hematological malignancies." (PMID 40564907, 2025). "Notably, LAML showed the significant overexpression of DDX3X, indicating its potential role in leukemogenesis, which is consistent with previous research on DDX3X’s involvement in RNA metabolism and dysregulation in hematological malignancies." (PMID 40564907, 2025). "Recent studies have reported the role of several DHX9-like genes including DDX41, DDX3X, and DHX32 in hematological diseases." (PMID 37305700, 2023).
neurodegenerative disease (2 papers, 2020 to 2022). A disorder of the central nervous system characterized by gradual and progressive loss of neural tissue and neurologic function. "DDX3X is also the key component of ribonucleoprotein (RNP) granules composed of mRNA and protein, a pathological hallmark of many neurodegenerative diseases." (PMID 35392274, 2022).
hematological cancer (1 paper, 2023). "This may be simply attributed to the expression levels of RocA targets (eIF4A1, eIF4A2 and DDX3X), which are much higher in hematological cancer tissues than in normal tissues (data not shown)." (PMID 36725859, 2023).
neurological disorder (1 paper, 2020). "DDX3X promotes innate immune responses and hypomorphic mutations of DDX3X have been linked to neurological disorder and mental retardation." (PMID 33137198, 2020).
DDX3X also shares sentences with these, for which no sentence is quoted: gallbladder cancer (5 papers); brain cancer (3); head and neck cancer (3); movement disorder (3); pulmonary fibrosis (3); acute lymphoblastic leukemia (2); adenocarcinoma (2); embryonal carcinoma (2); frontotemporal dementia (2); Intellectual Disability Syndrome (2); metastatic cancer (2); retinoblastoma (2); Rett syndrome (2); skin cutaneous melanoma (2); adenoma (1); AIDS (1); Alcoholism (1); Alpha-thalassemia (1); apraxia (1); Ataxia (1); Autoimmunity (1); blood cancers (1); Bosch-Boonstra-Schaaf optic atrophy syndrome (1); Brachycephaly (1); brain glioma (1); brain tumors (1); cerebellar tumor (1); Cerebral ischemia (1); cerebral palsy (1); cervical adenocarcinoma (1).
A further 57 diseases each share a sentence with DDX3X in 1 paper.